CD4 (CD4 molecule)
Diseases named in the same sentence as CD4 in open-access papers (continued):
Sharing a sentence is not in itself a finding about the gene and the disease.
rosacea (16 papers, 2016 to 2026). A chronic erythematous skin disorder that affects the face. "To investigate whether the reduced incidence of rosacea in the elderly is associated with a similar imbalance in adaptive immunity, we measured dermal CD4+ T cell populations using immunofluorescence." (PMID 39692542, 2024). "In patients with rosacea, the expression levels of CD4+ and CD8+ T cells are elevated, along with an upregulation of polarization genes associated with Th1 and Th17 cells." (PMID 41431076, 2025). "Previous studies have demonstrated that in an LL-37-induced rosacea-like mouse model, topical application of tofacitinib significantly improved rosacea-like phenotypes, reduced CD4+ T cell and mast cell infiltration, and suppressed dermal angiogenesis." (PMID 41459541, 2025). "Rosacea patients also showed elevated LL-37 expression and enhanced CD4+ T-cell infiltration, highlighting TLR7 and LL-37 as crucial molecular triggers in disease pathogenesis." (PMID 41373451, 2025). "Given that rosacea is characterized by inflammatory cell infiltration and vascular proliferation, we further assessed CD4+ T cells and CD31+ blood vessels in the skin." (PMID 40346694, 2025). "In vivo experiments further revealed that skin barrier dysfunction significantly elevates STAT3 expression and augments CD4+ T-cell infiltration in LL37-induced rosacea-like lesions in mice." (PMID 39044833, 2024). "Previous studies have shown that CD4+ T cells are integral to the pathophysiology of rosacea, characterized by an increased abundance of CD4+ T cells and polarization toward Th1/Th17 cell phenotypes within rosacea skin lesions." (PMID 39692542, 2024). "In one study, rosacea skin biopsies exhibited elevated levels of CD4+ T-cells, particularly Th1 and Th17 subtypes." (PMID 38450615, 2024). "Compared with HC, the proportions of infiltrated M1 macrophages, M0 macrophages, gamma delta T cells, and activated memory CD4 + T cells increased most in rosacea lesions, while resting mast cells and resting dendritic cells decreased most." (PMID 38321132, 2024). "Our previous study revealed that AQP3 is highly expressed in the epidermis and CD4+ T cells of patients with rosacea and experimental mice." (PMID 39692542, 2024). "Our findings reveal that AQP3-mediated activation of NF-κB in keratinocytes and activation of STAT3 in CD4+ T cells acted synergistically and contributed to the inflammation in rosacea." (PMID 37928265, 2023). "In summary, AQP3 functions as a proinflammatory regulator in keratinocytes and CD4+ T cells of rosacea skin." (PMID 37928265, 2023). "Eventually, the TLR7/NFκB/mTORC1 axis promoted the production of rosacea-correlative cytokines and chemokines, leading to the migration of CD4+ T cells, which is involved in the process of rosacea development." (PMID 37780385, 2023). "Ultimately, TLR7/NFκ B/mTORC1 axis promotes the production of cytokines and chemokines, leading to the migration of CD4+T cells, which are infiltrated in the lesional skin of rosacea." (PMID 37780385, 2023). "In the present study, our results reveal that epidermal AQP3 plays a proinflammatory role in rosacea pathogenesis by activating NF-κB signaling and cells to release chemokines, which recruit CD4+ T cells to lesions in the skin." (PMID 37928265, 2023). "Through immunofluorescence assays, we found that the expression of AQP3 in CD4+ T cells was enhanced in rosacea patients." (PMID 37928265, 2023). "The present study demonstrates that AQP3 is upregulated in the epidermal keratinocytes and dermal CD4+ T cells of rosacea patients and model mice." (PMID 37928265, 2023). "Here, we report that aquaporin 3 (AQP3), a channel protein that mediates the transport of water/glycerol, was highly expressed in the epidermis and CD4+ T cells of both rosacea patients and experimental mice." (PMID 37928265, 2023). "As described in previous studies, the infiltration of CD4+ T cells and Th1/Th17 polarized cells is essential in the pathogenesis of rosacea." (PMID 34899707, 2021).
rosacea (continued). "Interestingly, the clinical subtypes of rosacea exhibited differences in CD4+ elevation, with the papulopustular subtype displaying the greatest elevation." (PMID 38450615, 2024). "The current understanding of adaptive immunity in rosacea is limited, with studies indicating a high prevalence of CD4+ T cell infiltration around hair follicles and blood vessels in affected skin lesions, while there is no significant increase in CD8+ T cells." (PMID 37626650, 2023). "In consideration of the chemotactic effect of chemokines on immune cells, as well as the enrichment of immune cells in rosacea lesions, we performed CD4 immunostaining and found infiltration of CD4+ T cells induced by LL37 was eliminated by Tlr7 siRNA in the dermis of rosacea-like mice." (PMID 37780385, 2023). "Moreover, to determine the AQP3-mediated synergistic effect between keratinocytes and CD4+ T cells in the pathogenesis of rosacea, we perform the t-cell chemotaxis experiment." (PMID 37928265, 2023). "Interestingly, some N2 neutrophils in rosacea patients and mouse models exhibit anti-inflammatory effects by regulating vascular factors and inhibiting CD4+ T cell proliferation." (PMID 37626650, 2023). "Studies have found that there is a significant infiltration of CD4+ T cells in the skin lesions of patients with rosacea, predominantly comprising helper T cells (Th) 1 and Th17 cells, suggesting that adaptive immune responses also play a role in the pathogenesis of rosacea." (PMID 40821784, 2025). "Therefore, in the pathogenesis of rosacea, a positive feedback loop forms between the innate immune system represented by macrophages and the adaptive immune system mediated by CD4+ T cells, continuously amplifying the immune inflammatory response and promoting disease progression." (PMID 40821784, 2025). "Hence, we wondered whether the elevated expression of AQP3 in CD4+ T cells is important to rosacea pathogenesis." (PMID 37928265, 2023). "The infiltration of CD4+ T cells and the expression of Stat1, Stat3, and IL-17A were repressed by EGCG treatment in rosacea-like mice." (PMID 36937834, 2023). "TR B cell %lymphocyte, CD25 on IgD− CD24− B cell, and HLA DR on CD14− CD16+ monocyte are risk factors for the onset of rosacea, while central memory CD4− CD8− T cell AC, CCR7 on naive CD4+ T cell, CD14+ CD16− monocyte AC, and CD62L − mDC are protective factors for the onset of rosacea." (PMID 41431076, 2025). "Furthermore, we isolated CD4+ T cells obtained from dermal cell suspensions obtained from LL37-induced rosacea-like skin samples and verified that AQP3 was elevated in CD4+ dermal T cells but not in CD4- dermal T cells." (PMID 37928265, 2023).
Atrophy (15 papers, 2008 to 2025). Any weakening or degeneration, especially through lack of use. "Acute infectious diseases and stress are known to cause thymic atrophy through depletion of immature CD4+CD8+ thymocytes." (PMID 38316920, 2024). "In the scurfy model, autoimmune-mediated thymic aberrations include severe post-developmental atrophy associated with enhanced apoptosis of CD4+CD8+ double-positive (DP) cells and concomitantly increased frequencies of CD4SP and CD8+ SP (CD8SP) cells." (PMID 38164128, 2023). "Laboratory animal thymus atrophy via CD4+CD8+ lymphocyte apoptosis has been associated with any type of stress, such as restraint, irritation, trauma, or social stress, which is mediated by glucocorticoid release from the adrenal cortex." (PMID 18464053, 2008). "TDCA treatment alone caused villous atrophy, increased CD4+ T cells, Natural Killer cells, and two important immunoregulatory proteins, Qa-1 and NKG2D expression on T cells while decreasing T-regulatory cells in intraepithelial lymphocytes (IELs) in C57BL/6J mice." (PMID 36639805, 2023). "Phenotypes of immunosenescence include thymic atrophy, reduced numbers of naïve T cells, increased numbers of memory T cells, and a reversal of the CD4/CD8 ratio, all of which directly influence immune responses in aged individuals." (PMID 41221290, 2025). "Renal biopsy in the high-CD4 group presented with more severe glomerular lesions, higher density of interstitial inflammation, and more severe tubular atrophy/interstitial fibrosis than in the low-CD4 group." (PMID 39654881, 2024). "We examined the cross-sectional association between thymic atrophy, evaluated as the number of CD3+CD4+CD45RA+CD31+ cells [recent thymic emigrants (RTE)/μL], and MBD-related factors [(serum PTH, FGF23, and alkaline phosphatase (ALP) level] in 125 patients with non-dialysis dependent CKD." (PMID 30692566, 2019). "We have recently shown that plasma anti-CD4 IgGs contribute to poor CD4+ T cell recovery during suppressive ART via antibody-mediated cytotoxicity (ADCC) against CD4+ T cells, and that plasma anti-CD4 IgG levels are associated with worse cognitive performance and specific brain area atrophy." (PMID 34985329, 2022). "S. japonicum can also induce thymic atrophy with the accumulation of both CD8+CD28- T cells and CD4+CD28- T cells." (PMID 34113341, 2021). "The phenotypes of infiltrates (CD4+, CD8+, B220+, pan NK+ CD11b+ and Mac3+) in the kidneys with atrophy were further examined using FACS analysis." (PMID 27649757, 2016). "However, in a case described by Nanri with cerebellar atrophy, Purkinje cell loss and mild Bergmann gliosis, no lymphocytic infiltration was observed (CD3-, CD4-, CD8-, CD20-, CD68-, CD79A-)." (PMID 32244870, 2020).
cerebral infarction (15 papers, 2014 to 2025). An ischemic condition of the brain, producing a persistent focal neurological deficit in the area of distribution of the cerebral arteries. "MRI revealed that the relative cerebral infarct volume was significantly reduced in recipients of P2X7-KO CD4+T cells compared to those receiving WT CD4+T cells." (PMID 40948793, 2025). "In this study, we observed a reduction in CD4 + T cells during cerebral infarction, aligning with the results of previous studies." (PMID 40303468, 2025). "Animal experiments have shown that CD4 + T cell-mediated responses promote B cell infiltration into the central nervous system following cerebral infarction, likely involving additional interactions with microglia and infiltrating peripheral myeloid cells." (PMID 40303468, 2025). "We also found that GPR55 inactivation diminished CD4+T-cell infiltration in the brain, which was accompanied by diminished brain infarction and neurological outcome improvements." (PMID 38334672, 2024). "The violin diagram showed the infiltration of B cells naïve, T cells CD8, T cells CD4 naïve, monocytes, macrophages M0, macrophages M2, dendritic cells resting, and neutrophils in the cerebral infarction samples significant difference compared with the control group." (PMID 36755220, 2023). "Berczi70 suggested that cerebral infarction causes increased functional activity of the hypothalamic–pituitary–adrenal axis, producing large amounts of adrenocorticotropic hormones, which decreases the number of CD3+ and CD4+ T lymphocytes, thus suppressing the immunity of the body." (PMID 38360841, 2024). "In a phase II clinical trial study, fingolimod reduced brain infarct volume and BBB permeability, as well as the number of CD4+ T cells and CD8+ T cells in the blood of IS patients." (PMID 35140708, 2021). "It was found that CD8+ T-cells appeared as early as 3 h after cerebral infarction, whereas CD4+ T-cells appeared as early as 24 h after cerebral infarction, in which CD8+ T-cells may be related to neuronal death while CD4+ T-cells may play a role in tissue repair." (PMID 38550918, 2024).
chronic myeloid leukemia (15 papers, 2010 to 2023). "It has also been reported that an increased amount of CD4+ effector memory T cells was found in IFNα treated chronic myeloid leukemia patients." (PMID 37082269, 2023). "In the recent past, it has repeatedly been reported that CD4 cells play an important role in the immunology of chronic myeloid leukaemia." (PMID 24348684, 2013). "In addition, there was a case of myeloid sarcoma (extramedullary counterpart of chronic myeloid leukaemia) in an HIV positive female who had a CD4 count of 1626 cells/ul." (PMID 26091519, 2015). "Based on our previous finding, to further characterize the immune status, T cell proliferative history was analyzed in CD4+ and CD8+ T cells from chronic myeloid leukemia (CML) patients." (PMID 20470401, 2010). "An additional study reported lower response frequency in comparison to chronic myeloid leukaemia patients and another detected T cell responses (> 30 IFN-γ releasing cells/105 cells), but failed to dissect the relative contribution of the CD4+ and CD8+ T cell subsets." (PMID 37503339, 2023).
diabetic nephropathy (15 papers, 2013 to 2026). "In a mouse model of diabetes, mycophenolate mofetil attenuated diabetic nephropathy by reducing T lymphocyte infiltration in the kidneys, with an increase in IL‐17A+ CD4+ T cells observed as diabetic nephropathy progressed." (PMID 39946217, 2025). "The inhibition of DNMT1 with 5-aza-2′-deoxycytidine (5-Aza) caused regulatory T cells to co-express CD4 and CD25 (CD4+CD25+), leading to significantly improved outcomes in mice with diabetic kidney disease." (PMID 39595187, 2024). "Animal models of diabetic nephropathy have shown helper T cells (CD4 +), cytotoxic (CD8 +) T cells and small numbers of T-regulatory cells in kidney." (PMID 35445345, 2022). "In kidney biopsy samples of T2D patients with diabetic nephropathy CD4+ IL-17+ T cells were found, and IL-17A was the key cytokine produced by these cells." (PMID 32961903, 2020). "In conclusion, we demonstrated that MMF treatment attenuates diabetic nephropathy by decreasing CD4+ T cell infiltration and its related cytokines and chemokines." (PMID 26345532, 2015). "Seo and his colleagues reported that Mycophenolate Mofetil can alleviate diabetic nephropathy in db/db mice, followed by decreased albuminuria, attenuated mesangial expansion, and profibrotic mRNA expressions through downregulating the infiltrated CD4+ and CD8+ T cells." (PMID 36969169, 2023). "However, LADA patients' CD4+ T lymphocytes H3 acetylation was not related to fasting blood glucose, postprandial blood glucose, fasting C-peptide, postprandial C-peptide, age, duration of the disease, diabetic nephropathy, and cardiovascular disease." (PMID 26839444, 2015). "Gal-9 induces apoptosis in CD4+Tim-3+ TH1 cells, and Gal-9-Tim-3 pathway negatively regulates TH1 immunity, thus the elevation of serum Gal-9 may be beneficial in the progression of diabetic nephropathy by negatively regulating the immune responses and inflammation." (PMID 23339460, 2013).
encephalomyelitis (15 papers, 2012 to 2025). Inflammation of the brain and the spinal cord. "IL-10 is increased in the CNS during SINV encephalomyelitis and is an important modulator of CD4+ T cell responses and disease severity during CNS infection with strains of SINV that differ in virulence." (PMID 36016413, 2022). "Previous studies have shown that fatal NSV-induced encephalomyelitis is an immunopathologic process driven by CD4+ T cells, although knowledge of the mechanisms of immune-mediated neuronal damage remains incomplete." (PMID 36016413, 2022). "The most striking observation in the encephalomyelitis patient was high expression of inducible T cell costimulatory receptor (ICOS) on all subtypes of CD4 +T helper cells and on CD8+ cytotoxic T cells." (PMID 34215689, 2021). "Activation and central nervous system (CNS) recruitment of myelin-specific CD4 T cells was analyzed by flow cytometry during encephalomyelitis induced by a glia tropic murine coronavirus." (PMID 26559484, 2015). "This pattern is clearly demonstrated during JHMV encephalomyelitis, in which both CD4+ and CD8+ T cells are essential in mediating virus clearance accompanied by tissue damage." (PMID 24156369, 2013). "The present study thus aimed to determine the role of TIMP-1 in regulating CD4+ T cell recruitment into the CNS parenchyma, as well as potential functional consequences of altered CD4+ T cell distribution on JHMV induced encephalomyelitis." (PMID 24156369, 2013). "The association between irAE development and ICOS+CD4+ T cells was forecasted in a previous study demonstrating that increased frequency of peripheral ICOS+CD4+ T cells was ameliorated by steroid treatment in patients with immune-related hepatitis and encephalomyelitis." (PMID 40198121, 2025). "However, one patient on DRV/r monotherapy with a CD4 nadir of 17 cells/μL was hospitalized with HIV encephalomyelitis at Week 24, with HIV RNA 2500 copies/mL in the CSF and 125 copies/mL in the plasma." (PMID 25394035, 2014). "Previous studies have shown that the production of IL-10, a cytokine that controls inflammation in part by regulating differentiation of CD4+ T cells, is an important determinant of the outcome of SINV-induced encephalomyelitis." (PMID 36016413, 2022). "The costimulatory receptor inducible T cell costimulatory receptor (ICOS) was expressed on a high proportion of CD4+ and CD8+T cells as encephalomyelitis symptoms peaked and then gradually decreased in parallel with clinical improvement." (PMID 34215689, 2021). "In conclusion, our results suggest a potential role for ICOS on CD4+ and CD8+T cells in mediating encephalomyelitis and other serious irAE." (PMID 34215689, 2021). "Interestingly, Tamoxifen-treated Cre-ERT2-Gata3fl/fl CD4 effector cells Tcra-/- recipients were resistant to transfer EAE in comparison to vehicle treated controls, indicating that late maintenance levels of GATA3 are also required for Th17-mediated encephalomyelitis." (PMID 37449212, 2023).